RCSD1 (RCSD domain containing 1)
Description:
Stress-induced phosphorylation of CAPZIP may regulate the ability of F-actin-capping protein to remodel actin filament assembly.
Synonyms: CAPZIP; MK2S4; MGC21854
Tractability: PROTAC: its protein half-life has been measured.
Gene: Protein-coding gene on chromosome 1 (167,629,660 to 167,708,706, forward strand). Ensembl gene ENSG00000198771.
Gene Ontology:
Molecular function: actin filament binding; phosphatidylinositol phosphate binding; retromer complex binding
Biological process: cellular hyperosmotic response; protein localization to endosome; retrograde transport, endosome to Golgi; skeletal muscle contraction
Cellular component: actin filament; early endosome; WASH complex; cytosol
Genetic constraint (gnomAD): Loss-of-function variants: 26 observed, 39.6 expected, observed/expected ratio (o/e) 0.66, 90% interval 0.48 to 0.91. The upper end of that interval is the gene's LOEUF score, 0.91, which puts it in group 3 of 6, group 1 being the genes least tolerant of losing a copy. Missense variants: 569 observed, 524.43 expected, observed/expected ratio (o/e) 1.09, 90% interval 1.01 to 1.16. Synonymous variants: 218 observed, 210.32 expected, observed/expected ratio (o/e) 1.04, 90% interval 0.93 to 1.16.
Homologues: Orthologues: chimpanzee RCSD1 (97% identical), macaque RCSD1 (93% identical), rabbit RCSD1 (71% identical), pig RCSD1 (68% identical), dog RCSD1 (66% identical), rat Rcsd1 (64% identical), mouse Rcsd1 (64% identical), guinea pig RCSD1 (64% identical), tropical clawed frog rcsd1 (35% identical), zebrafish dub (23% identical), zebrafish zgc:153184 (21% identical), Drosophila melanogaster FAM21 (18% identical). Paralogues in human: WASHC2C (21% identical), WASHC2A (21% identical).
Diseases named in the same sentence as RCSD1 in open-access papers:
RCSD1 is named in the same sentence as 31 diseases in open-access papers, as found by Europe PMC text mining. Sharing a sentence is not in itself a finding about the gene and the disease. The quoted sentences say what the papers report.
lung carcinoma (2 papers, 2022 to 2024). "RCSD1 may serve as a prognostic biomarker for the prognosis associated with immune infiltration in lung cancer." (PMID 36311703, 2022). "The results showed that RCSD1 was correlated with immune cells in lung cancer, moreover, increased tumor immune-infiltrating cells and increased RCSD1 expression were associated with better prognosis of lung cancer patients." (PMID 36311703, 2022). "Previous research has demonstrated that RCSD1 is positively related to infiltrating macrophages in lung cancer." (PMID 38903921, 2024). "The relationship between RCSD1 expression and the clinical data of lung cancer patients was analyzed using the UALCAN database." (PMID 36311703, 2022). "The expression of RCSD1 is closely related to the immune infiltration of lung cancer cells, and RCSD1 may partly affect the prognosis by regulating the immune infiltration in lung cancer patients." (PMID 36311703, 2022). "In addition, we explored the relationship between RCSD1 and clinical case parameters of lung cancer, immune cells, and tumor immunotherapy." (PMID 36311703, 2022). "Therefore, we further explored the relationship between RCSD1 and the immune mechanisms of lung cancer." (PMID 36311703, 2022). "In human cancer, RCSD1 plays an important role in the tumor microenvironment (TME) and is significantly associated with the expression of immune infiltrating cells (TIL) in lung cancer." (PMID 36311703, 2022).
B-cell acute lymphoblastic leukemia (1 paper, 2015). A neoplasm of lymphoblasts committed to the B-cell lineage, typically composed of small to medium-sized blast cells. "The RCSD1 gene has recently been identified as a novel gene fusion partner of the ABL1 gene in cases of B-cell Acute Lymphoblastic Leukemia (B-ALL)." (PMID 26600955, 2015).
cholangiocarcinoma (1 paper, 2022). A carcinoma that arises from the intrahepatic biliary tree (intrahepatic cholangiocarcinoma) or from the junction, or adjacent to the junction, of the right and left hepatic ducts (hilar cholangiocarcinoma). "Only CHOL (Cholangiocarcinoma) and KIRC (Kidney renal clear cell carcinoma) tumors had higher RCSD1 expression than normal tissues." (PMID 36311703, 2022).
Esophageal carcinoma (1 paper, 2022). A primary or metastatic malignant neoplasm involving the esophagus. "Meanwhile, poor RFS of TGCT, SARC, OV (Ovarian serous cystadenocarcinoma) and UCEC were correlated with low expression of RCSD1, and poor RFS of ESCC, ESCA (Esophageal carcinoma), HNSC and KIRP was significantly associated with high expression of RCSD1." (PMID 36311703, 2022).
Glioblastoma multiforme (1 paper, 2022). "However, the total RCSD1 protein expression was higher in the GBM (Glioblastoma multiforme), PAAD (Pancreatic adenocarcinoma), KIRC, and UCEC primary tissues than in the normal tissues." (PMID 36311703, 2022).
head and neck squamous cell carcinoma (1 paper, 2022). A squamous cell carcinoma that arises from any of the following anatomic sites: lip and oral cavity, nasal cavity, paranasal sinuses, pharynx, larynx, and salivary glands. "Using GEPIA, we found that low RCSD1 expression was associated with poor OS in HNSC (Head and Neck squamous cell carcinoma), KIRC, THYM, LUAD, SARC (Sarcoma), and SKCM; low RCSD1 expression in both LGG (Brain Lower Grade Glioma) and UVM (Uveal Melanoma) was associated with better OS." (PMID 36311703, 2022).
lymph node metastasis (1 paper, 2022). "In addition, we selected LUAD and LUSC focusing on the correlation of RCSD1 and patient clinical data, found that RCSD1 was associated with individual tumor stage, patient age, smoking history, and lymph node metastasis in LUAD patients." (PMID 36311703, 2022).
Skin Cutaneous Melanoma (1 paper, 2022). "As we can see, the RCSD1 expression levels differ significantly in the BLCA, SKCM (Skin Cutaneous Melanoma), STAD and THCA tumor pathological stage." (PMID 36311703, 2022).
uterine carcinosarcoma (1 paper, 2022). A usually aggressive malignant neoplasm arising from the uterine corpus and less often the cervix. "Meanwhile, the analysis results showed that high RCSD1 expression was associated with better RFS in CHOL and UCS (Uterine Carcinosarcoma) patients, and instead, high RCSD1 expression was associated with poor RFS in LGG." (PMID 36311703, 2022).
tumor (2 papers, 2022 to 2024). "For example, both CD37 and RCSD1 are linked to recruitment of anti-tumour immune cells and improved prognoses." (PMID 38902676, 2024). "The relationship between RCSD1 and patient prognosis, clinical data, gene mutations, tumor immune infiltration, tumor immune markers, and immunotherapy provides new insights for future clinical diagnosis and treatment." (PMID 36311703, 2022). "However, RCSD1 expression was negatively associated with tumor purity." (PMID 36311703, 2022). "In our study, we used a variety of databases to analyze RCSD1 expression, prognostic value, molecular functional networks, genetic alterations, and potential relationships with tumor immune microenvironment in pan-carcinomas." (PMID 36311703, 2022). "We concluded that, firstly, compared with normal tissues, the expression level of RCSD1 in tumor tissues is lower." (PMID 36311703, 2022). "We look forward to further studies of RCSD1 to progressively elucidate the biological role of RCSD1 in the tumor immune micro-environment and prognosis." (PMID 36311703, 2022). "The purpose of this study was to explore the role of RCSD1 in human cancer, thereby providing insights into new anti-tumor strategies." (PMID 36311703, 2022). "However, the high expression of RCSD1 in only a few tumors (LGG, UVM, TGCT, and ESCC) was associated with poor tumor patient prognosis (OS)." (PMID 36311703, 2022). "However, the biological process and molecular mechanism of RCSD1 in tumor progression need more basic experimental studies." (PMID 36311703, 2022). "At the same time, the expression of RCSD1 was significantly different in most of the tumor immune subtypes and tumor immune molecular subtypes, which suggested that RCSD1 may be involved in regulating tumor immune related processes, thereby affecting patient prognosis." (PMID 36311703, 2022). "There may be several reasons for the influence of RCSD1 on the prognosis of tumor patients." (PMID 36311703, 2022). "Next, we explored whether RCSD1 expression varied across different stages of the same tumor." (PMID 36311703, 2022). "To further assess the effect of RCSD1 on the tumor micro-environment (TME), we first used the CIBERSORT method to analyze the distribution of 22 immune cells in different high and low RCSD1 expression groups." (PMID 36311703, 2022). "Thus, we confirmed that RCSD1 is widely involved in regulating multiple immune molecules in LUAD and LUSC, thereby affecting immune infiltration in the tumor micro-environment." (PMID 36311703, 2022).
cancer (1 paper, 2022). A tumor composed of atypical neoplastic, often pleomorphic cells that invade other tissues. "We first analyzed the gene mutation frequency, mutation types, mutation site of RCSD1 in pan-cancer by using the cBioportal web site, RCSD1 mutation rates were found to be high in CHOL, BLCA, LIHC, BRCA, LUAD, SARC, and LUSC." (PMID 36311703, 2022). "Similarly, in LUSC group, the expression of RCSD1 is associated with individual cancer stage, and stage 1 patients’ RCSD1 expression level is higher than that in stage 4." (PMID 36311703, 2022). "First, we mainly explored the analysis of RCSD1 expression and immune related processes in pan-cancer." (PMID 36311703, 2022). "In our study, RCSD1 (NP_443094.3) was found to be phosphorylated at multiple sites of the pan-cancer." (PMID 36311703, 2022). "RCSD1 is related to individual cancer stage in LUAD patients, RCSD1 expression levels in stage 1 was higher than stage 3 and stage 4." (PMID 36311703, 2022). "Through previous studies, we learned that genetic mutations in RCSD1 may induce hematological malignancies, so here, we investigated the type and status of mutation and mutations that may occur in the RCSD1 gene in pan-cancer, and the effect of the RCSD1 gene mutation on patient prognosis." (PMID 36311703, 2022). "In parallel, we retrieved 50 proteins that showed interactions with RCSD1 in pan-cancer by the String database." (PMID 36311703, 2022). "In this study, we applied the Timer database to analyze the expression levels of RCSD1 in different cancer types." (PMID 36311703, 2022). "Our analysis of RCSD1 total protein and phosphorylated proteins in pan-cancer using CPTAC database revealed that RCSD1 total protein expression was lower in COAD, LIHC, and LUAD tissues than in normal tissues." (PMID 36311703, 2022). "This study improves our understanding of the relationship between RCSD1 and pan-cancer, but several limitations remain." (PMID 36311703, 2022). "Therefore, we investigated the mRNA and protein expression of RCSD1 in pan-cancer through public databases." (PMID 36311703, 2022). "RCSD1 is a cytoskeletal regulator that has been confirmed to undergo genetic mutations in hematological tumors, but the mechanisms of RCSD1 in pan-cancer and its impact on patient prognosis have not been studied." (PMID 36311703, 2022). "Taken together, our results demonstrate that RCSD1 is significantly differentially expressed in different human tumors and that its expression level correlates with clinical case characteristics and prognosis of pan-cancer patients." (PMID 36311703, 2022). "Therefore, in future clinical work, the detection of RCSD1 expression levels in cancer patients could be used to evaluate the disease and predict the prognosis of patients." (PMID 36311703, 2022).
Kidney (1 paper, 2022). "Finally, RCSD1 expression was correlated with lymph node metastasis status in LUAD patients, and patients in the N0 group expressed higher levels of RCSD1 than in the N2 group." (PMID 36311703, 2022).
RCSD1 also shares sentences with these, for which no sentence is quoted: Bladder Urothelial Carcinoma (1 paper); brain disorder (1); Breast invasive carcinoma (1); cervical squamous cell carcinoma (1); endometrial carcinoma (1); esophageal squamous cell carcinoma (1); hematological malignancies (1); lung adenocarcinoma (1); lung squamous cell carcinoma (1); lymph node (1); metastatic melanoma (1); ovarian serous cystadenocarcinoma (1); pancreatic adenocarcinoma (1); prostate adenocarcinoma (1); rectum adenocarcinoma (1); sarcoma (1); Stomach adenocarcinoma (1); Thyroid carcinoma (1); uveal melanoma (1).